RNU7-18P (RNA, U7 small nuclear 18 pseudogene)
Synonyms: U7.18; RNU7-142P
Gene: Small nuclear RNA gene on chromosome 3 (196,072,819 to 196,072,880, forward strand). Ensembl gene ENSG00000252174.
Homologues: Orthologues: macaque U7 (92% identical). Paralogues in human: RNU7-28P (92% identical), RNU7-8P (92% identical), RNU7-13P (90% identical), RNU7-45P (90% identical), RNU7-6P (90% identical), RNU7-14P (89% identical), RNU7-2P (89% identical), RNU7-40P (89% identical), RNU7-41P (89% identical), RNU7-1 (87% identical), RNU7-128P (87% identical), RNU7-21P (87% identical), and 143 more.